IDH1 (isocitrate dehydrogenase (NADP(+)) 1)
Diseases named in the same sentence as IDH1 in open-access papers (continued):
Sharing a sentence is not in itself a finding about the gene and the disease.
tumor (continued). "IDH1 mutational status and its association with outcome were assessed in 75 of our patients (10 tumours with mutations vs 65 non-mutated tumours, p<0.001)." (PMID 24039914, 2013). "Depletion of α-KG, an essential citric acid cycle intermediate, in IDH1 mutant tumor cells may play a role during tumor development but competitive inhibition by D-2HG of the 60 known α-KG-dependent enzymes appears to be a more important factor." (PMID 24252742, 2013). "PCR sequencing of IDH1 confirmed the maintenance of the heterozygous c.395G > A mutation [NM_005896.2] resulting in the R132H conversion in IDH1, similarly to the parental tumor (data not shown)." (PMID 24252742, 2013). "The product of IDH1/IDH2 mutations, d-2HG, can be detected in tumor samples." (PMID 23847760, 2013). "Patients were analyzed according to IDH1 status and tumor-related factors." (PMID 23840696, 2013). "The resulting IDH1 (R132H) tumor model was designated as JHH-273." (PMID 24077805, 2013). "IDH1 mutation results in the formation of the oncometabolite 2-hydroxyglutarate and the induction of the hypoxia-inducible factor subunit HIF-1α, a transcription factor that facilitates tumour growth and angiogenesis in low oxygen conditions." (PMID 23451042, 2013). "This pericyte proliferation was observed in all (8/8) cases of IDH1 mutant tumours." (PMID 23451042, 2013). "A striking observation was the strong negative association of this clinicopathological subgrouping with the more pronounced arcade-like vascular appearance that may be frequently observed in IDH1 wild type tumours." (PMID 23451042, 2013). "In all three instances the IDH1- mutation observed in the primary tumor was no longer detected in the respective recurrent tumors (ID49562, ID22328 and ID25172)." (PMID 22844452, 2012). "Thus far, studies that have sought to determine the contribution of mutant IDH1 in tumor survival and proliferation have conflicted, making the potential of mutant IDH1 as a therapeutic target difficult to defend." (PMID 22885298, 2012). "Similarly, tumor biomarkers known to predict response to adjuvant therapy or overall survival (such as 1p/19q, IDH1/2, and MGMT-methylation) should also be incorporated into future analyses." (PMID 23087667, 2012). "In one tumor pair the IDH1- mutation present in the primary tumor was no longer detectable upon tumor recurrence (ID22670)." (PMID 22844452, 2012). "The increased incidence of the G500 allele and the absence of IDH1 mutations provide justification for the NDTMM GBMs being a molecularly distinct subgroup of tumor." (PMID 22046342, 2011). "In the ALT positive tumor cohort, the younger age of individuals with IDH1 mutations was significant compared with those without IDH1 mutations (median age 36 versus 52, 25th to the 75th percentile 26–40.5 versus 48–61, p<0.001)." (PMID 22046342, 2011). "We were not able to culture tumour cells presenting IDH1 mutations originating from currently proceeded 10 tumours; the same results were observed in 7 samples of archival material." (PMID 21326241, 2011). "The variable IDH1 mutation was not identified as an independent predictor for longer survival in the oligodendrocytic tumour group." (PMID 21559010, 2011).
tumor (continued). "IDH1 mutations occur in only a single allele (i.e. heterozygotic),suggesting the mutation acts in an oncogenic manner rather than being part of atypical tumor suppressor mutation to promote tumorgenesis." (PMID 21317451, 2010). "For this, incorporating genetic markers (e.g., IDH1 mutation, MGMT promoter methylation) with imaging features (e.g., signal intensity, diffusion metrics, perfusion parameters) was proposed, which provided a more accurate and dynamic measurement of tumor heterogeneity." (PMID 40432717, 2025). "Notably, our probe is designed to assess IDH1 mutations in excised tumor tissues rather than to locate tumor infiltration or deep‐seated tumors during surgery." (PMID 40171868, 2025). "Preclinical evidence suggested that the IDH1 mutation may contribute to immunosuppressive signaling and that the depletion of CD8+ T cells diminishes the anti-tumor activity of IDH1 inhibitors, which raises the possibility of combining IDH1 inhibitors with immunotherapy." (PMID 41236411, 2025). "Patients with high MRM score had a poor clinical outcome, which may be associated with that IDH1 wild-type, high grade tumor, 1p19q non-codeletion, and MGMT promoter nonmethylation were enriched in high MRM score." (PMID 38824202, 2024). "This epigenetic and metabolic shift in the tumor microenvironment, as demonstrated in these mouse models, suggests that immune checkpoint blockade coupled with the IFN-γ-TET2 axis can surmount immunosuppression, thereby providing a strategy to counteract the resistance to IDH1 mutation inhibitors." (PMID 39156971, 2024). "For this reason, our analysis could more accurately represent the entire heterogeneity of the tumor compared to tissue biopsy, explaining the detection of the IDH1 mutation in the cfDNA of a subgroup of patients negative on tissue." (PMID 38172718, 2024). "This evidence suggests that the epigenetic mechanism underlying the inhibition of tumor suppressor genes may be independent of the hypermethylated state induced by IDH1/IDH2 mutation." (PMID 39123479, 2024). "Furthermore, we observed a correlation between elevated MRM score and malignancy features characterized by older age, mortality, absence of IDH1 mutation, higher tumor grading, lack of 1p19q co-deletion, and MGMT promoter methylation." (PMID 38824202, 2024). "These structural features are generally preserved in IDH1 R132H1,3,14, but inherent catalytic deficiencies coupled with improved NADPH binding result in this mutant catalyzing D2HG production, albeit inefficiently though at great benefit to the tumor environment." (PMID 38710674, 2024). "However, with more precise knowledge of this tumor’s evolutionary history, we can see that such treatment will fail for one-fifth of its malignant cells, since the mutated IDH1 protein is no longer there." (PMID 39001492, 2024).
tumor (continued). "In particular, IDH1 mutation was detected in the cfDNA of 10 out of 21 patients harboring an IDH1 mutant tumor, and in 5 patients with IDH1 wild type tumor tissue (n = 41), suggesting that liquid biopsy may support tissue biopsy in the detection of IDH1 mutation." (PMID 38172718, 2024). "Additionally, the dysregulated production of 2-HG by mutant IDH1/2 alters cellular metabolism, impacting pathways involved in amino acid metabolism, redox balance, and biosynthesis, creating a favorable environment for tumor growth and survival." (PMID 39201639, 2024). "On the other hand, in our cohort eleven patients presented IDH1 mutated tumor tissue and no IDH1 mutation in plasma, suggesting that the blood-brain barrier could limit the release of cfDNA and consequently, the detection of IDH1 mutation." (PMID 38172718, 2024). "However, the association between tumor grade and the presence of IDH1 mutation (p = 0.10) was not statistically significant." (PMID 38172718, 2024). "These structural and dynamic discoveries not only highlight mechanistic properties of important tumor drivers, but also identify regions that may serve as selectivity handles when designing mutant IDH1 inhibitors requiring increasing selectivity or optimization against resistance mutants." (PMID 38710674, 2024). "Additionally, IDH1 R132Q drove enchondroma tumor formation in mouse models." (PMID 38710674, 2024). "Indeed, ample catalytic activity of IDH1/NADP+ was present in supernatants of lysed tumor cells." (PMID 37161052, 2023). "Our findings indicate that IDH1 wild-type HGG patients present greater NCF impairment, in executive functions particularly, compared to IDH1 mutant ones, suggesting that tumor growth kinetics may play a more profound role than other tumor and demographic parameters in clinical NCF of HGG patients." (PMID 36970174, 2023). "Accordingly, our findings indicate that baseline neurocognitive status may largely depend on the IDH1 mutation status rather than on the simplified tumor III and IV grading per se." (PMID 36970174, 2023). "IDH1-mutant cells display a reduced ability to induce reductive carboxylation under hypoxic circumstances, with a reliance on oxidative mitochondrial metabolism which in turn may result in decreased proliferation of tumour cells." (PMID 36286062, 2022). "The role of tumor size may depend on the underlying genetic make-up of the tumor: one study found an inverse relationship between neurocognitive function and lesion volume in patients with IDH1 wild type but not mutant tumors." (PMID 36033458, 2022). "It is unclear whether isocitrate dehydrogenases (IDH1/2) when not mutated have any role in gliomagenesis or tumor growth." (PMID 35877430, 2022). "Compared to the initial grossly resected tumor specimen, the recurrent tumor possessed loss of heterozygosity of 1p, 10q, 17q, and 19q chromosomes, as well as a new C228T TERT promoter mutation, while the status of wild-type IDH1/IDH2 and mutant BRAF V600E was unchanged." (PMID 36703629, 2022). "Interestingly, we observed that the contralateral compensatory activation of the operculum region was mostly dependent on some molecular parameters of the tumors, such as IDH-1 mutation, TERT mutation, and deletion of 1p19q, instead of the pathological grade of the tumor." (PMID 35720068, 2022). "Furthermore, and in agreement with its ROS scavenging activity, upregulation of IDH1 expression was observed following ionizing radiation and its silencing increased tumor sensitivity to radiation-induced senescence, both in vitro and in murine xenograft models of human GBM." (PMID 34764443, 2022).
tumor (continued). "In light of the difficulties of culturing IDH1 mutated patient-derived glioma cells in vitro and the lack of patient-derived IDH mutant in vitro and in vivo models, our approach provides a suitable alternative to investigate IDH1R132H-dependent alterations in tumor cell metabolism." (PMID 35628596, 2022). "In addition, the IDH1/2 genetic alterations can be also associated with abnormal expression of platelet-derived growth factor (PDGF), leading to the abnormal activation of microglia and promoting the tumor cell’s invasiveness." (PMID 36555334, 2022). "Further in vitro studies demonstrated that mutant IDH1/2 alters the TCA metabolic fluxes leading to increased dependence on glutaminolysis and compromised multiple DNA repair pathways, ultimately making tumor cells more susceptible to radiation and chemotherapy." (PMID 34764443, 2022). "Besides different treatment regimens for rGBM, no prognostic factor (including age, sex, KPS, recurrent tumor volume, IDH1 mutation status, and MGMT promotor methylation status) has been reported to exert a significant impact on OS and PFS." (PMID 36046037, 2022). "Importantly, the expression of none of these genes was associated with age, IDH1 mutation status, gender, tumor mutational burden and other confounder factors as confirmed by multivariate analysis (Spearman p-value > 0.05)." (PMID 36358647, 2022). "Furthermore, the observation that secondary tumor had IDH1/2 wild-type was consistent with prior studies that RIGs do not harbor IDH1/2 mutations." (PMID 35505351, 2022). "Therefore, presence of any IDH1 R132H staining at the margin proves presence of residual tumor." (PMID 34108566, 2021). "Moreover, we found that IDH1 level was associated with death but not age, gender or primary tumor location." (PMID 33468990, 2021). "We saw similar levels of tumor suppression in another independent study with HCT116 IDH1-mutant xenograft model, with smaller sample size (n = 5), where the combination therapy at lower dose of AZD6738 (25 mg/kg) and olaparib (25 mg/kg) was also effective in causing a significant tumor growth delay." (PMID 34027408, 2021). "Moreover, this tumor also exhibited positive staining for the IDH1." (PMID 34805184, 2021). "In the Phase I trial of the IDH1 inhibitor ivosidenib, a complete remission rate (CR) of almost 22% was achieved, but with a median duration of response of only 6.5 months and a median overall survival (OS) under 9 months, thus demonstrating rapid tumor escape mechanisms." (PMID 34176517, 2021). "The rationale of using metformin and chloroquine in order to disrupt the metabolism of IDH1-mutated solid tumors and to inhibit tumor growth was not supported by our clinical data, since ten out of twelve patients showed tumor progression during study treatment." (PMID 34069550, 2021). "Similarly, multivariate analysis showed that WHO grade IV (p = 0.001), SVZ involvement (p = 0.01), tumor-SVZ distance from 0 to 10 mm (p = 0.03), GTR (p = 0.05), chemotherapy (p = 0.003), and IDH1 mutation (p = 0.01) served as independent predictors for patient OS." (PMID 34490090, 2021). "This example shows that oncometabolites cannot be considered entirely under a negative light, because high levels of 2-HG may exert anti-tumor and chemosensitizing effects in IDH1/IDH2 mutated GBM." (PMID 34065551, 2021). "The tumor was negative for IDH1(R132) mutation and MGMT unmethylated." (PMID 33353026, 2020). "Strong correlations were noted between mutations in oncogenes and tumor suppressor genes and non-T cell-inflamed tumors with examples including IDH1 and GNAQ as well as less well-known genes including KDM6A, CD11c, and genes with unknown functions." (PMID 33106165, 2020).
tumor (continued). "However, none of the mutations are exclusively observed in one tumour type, suggesting a similar effect of all IDH1 and IDH2 mutations on tumourigenesis." (PMID 31728625, 2020). "Among ERGs that could be classified as tumor suppressors, KMT2D, KMT2C, ARID1A, ATRX, CREBBP, and PBRM1 were frequently mutated in many cancer types, whereas oncogenic ERGs were each mutated in specific cancer types, mainly IDH1 in LGG and DNMT3A in LAML." (PMID 32963031, 2020). "Whether multiple IDH1/2 mutations occurred in the same or different tumor subpopulations was not described." (PMID 32333643, 2020). "Furthermore, IDH1/2 mutations were associated with higher histological differentiation, but not tumor stage." (PMID 32293336, 2020). "Furthermore, tumours with wildtype IDH1 have a poorer prognosis than WHO-grade matched tumours that harbour IDH1 mutations, suggesting that high expression of the wildtype form of IDH1 may drive TK-RIG915 tumour progression." (PMID 33053751, 2020). "Consequently, the IDH1 mutation serves as a valuable diagnostic marker by assisting in the differentiation of tumour entities that are often indistinguishable through histopathological analysis alone, but have different treatments and prognostic profiles." (PMID 33302429, 2020). "Most important, and as it also occurs with the isocitrate dehydrogenase (IDH1) mutations, the presence of NSUN5 DNA methylation-associated silencing in human gliomagenesis identifies patients with good clinical outcome, which is an exceptional feature of people affected by this tumor type." (PMID 31428936, 2019). "In addition, SNHG18 expression showed an association with the clinical tumor grade and a negative correlation with mutation of isocitrate dehydrogenase 1 (IDH1)." (PMID 31798634, 2019). "Moreover, perhaps it is not a surprise that deletion of mutant IDH1 allele can occur during tumor recurrence, resulting in reduced 2-HG levels." (PMID 31652645, 2019). "Moreover, there was a significant difference in terms of tumor distribution in the cerebral lobes: IDH1-mutant tumors were mainly located in the temporal (50%) and frontal (40%) lobes, whereas IDH1-wild type tumors were most often located in the temporal lobe (47.5%)." (PMID 31275753, 2019). "However, the expression of vGlut1 was neither associated with IDH1 status nor with tumour grade (data not shown)." (PMID 30297697, 2018). "In both groups, high CD45, high CD4 count, high CD8 count, gender, receiving radiotherapy alone, TMZ therapy alone, salvage gamma knife (GKS) treatment, or tumor cells expressing IDH1 mutation, and MGMT methylation were all not significant prognostic factors under HR evaluation." (PMID 29910795, 2018). "In addition, a recent report claims mutations in IDH results in loss of function without elevation of D-2HG supporting that at least in some cases IDH1/2 may function as a typical tumor suppressor gene." (PMID 29439493, 2018). "Mutations on codon 132 or 172 of the IDH1 and IDH2 genes, respectively, results in “neo-enzymatic activity” with the production of the novel oncometabolite 2-hydroxyglutarate causing widespread methylation of the tumour cell DNA and altered regulation of histone methylation." (PMID 29098416, 2018). "Importantly, inhibition of mutant IDH1 may lead to the reprogramming of tumor metabolism, suggested by simultaneous changes in glutathione, glutamine, glutamate, and lactate." (PMID 29662077, 2018). "As such, any perturbation in redox homeostasis elicited by mutations in IDH1 may not be confined to the cytosol but have implications for tumor growth through altered regulation of mitochondrial metabolism." (PMID 29562167, 2018). "Thus, rather than attempting to decrease 2-HG synthesis in the clinic, the consumption of NADPH by mutant IDH1 may be exploited as a metabolic weakness that sensitizes tumor cells to ionizing radiation, a commonly used anti-cancer therapy." (PMID 29320744, 2018).